CD36 (CD36 molecule (CD36 blood group))
Diseases named in the same sentence as CD36 in open-access papers (continued):
Sharing a sentence is not in itself a finding about the gene and the disease.
Obesity (continued). "Muscle’s transcriptional remodelling fuels the greater GIR in CD36 deficiency and this adaptation might eventually fail in obesity or ageing." (PMID 39503770, 2025). "Specifically, these findings linked VAT to the upregulation of CD36, a scavenger receptor and FA-translocase well-established in cardiovascular disease progression, as an upstream event driving the dysfunction of Kir2.1 in obesity." (PMID 40996861, 2025). "Thus, Cd36 deficiency leads to LV leakage, late-onset obesity, and an increased risk of developing type 2 diabetes." (PMID 38798921, 2024). "Furthermore, overweight/obesity was associated with increased expression of CD36 and ANGPTL4 in tumor cells at the invasive front, suggesting altered lipid metabolism and metabolic reprogramming in the tumor cells of these patients." (PMID 39456610, 2024). "Deletion of Cd36 in a murine model caused discontinuous VE-cadherin junctions in lacteals, a process that has been shown to play a key role in chylomicron transport and diet-induced obesity." (PMID 38798921, 2024). "CD36 is a key molecule to limit β-cell function in T2DM associated with obesity." (PMID 37293508, 2023). "In addition to the protective effect on kidney function, we also determined the effect of CD36 peptide treatment on obesity-associated non-alcoholic fatty liver disease (NAFLD)." (PMID 37980376, 2023). "Knock out of TSP1 or CD36 improved obesity-associated kidney damage." (PMID 37980376, 2023). "As noted for WD-fed MR-Intact mice, WD also downregulated genes associated with extracellular matrix in SMC-MR-KO mice (Online Resources 26 and 27) and top upregulated genes also included those implicated in diabetes and obesity, such as Cd36, Txnip, Angptl4, Cyp1a1, and Fabp4." (PMID 36988733, 2023). "In addition to attenuation of obesity-induced inflammation and insulin resistence in obese mice, CD36 peptide treatment alleviated obesity-associated kidney or liver damage." (PMID 37980376, 2023). "Notably, in the current study, we revealed that CD36 peptide treatment effectively mitigated obesity-associated non-alcoholic fatty liver disease (NAFLD), as evidenced by reduced plasma ALT and AST levels, as well as decreased liver fat accumulation." (PMID 37980376, 2023). "In this study, we have examined the association between polymorphisms and hypermethylation of the CD36 gene promoter with obesity in Senegalese females with or without type 2 diabetes mellitus to identify novel molecular markers of these pathologies (obesity and type 2 diabetes mellitus)." (PMID 35982478, 2022). "In addition, lipid accumulation and significant upregulation of LPL and CD36 expression were discerned in N + tumor tissue samples and obesity cases, further strengthening the association of lipid metabolism with LNM." (PMID 36397145, 2022). "The CD36 role in obesity and its related complication type 2 diabetes prompted us to investigate its singles nucleotides polymorphisms and gene methylation association with obesity and obese-diabetic in Senegalese women." (PMID 35982478, 2022). "Moreover, obesity appears to be associated with greater expression of the transporters (CD36/SR-B2 and FATP4) at the transcript (mRNA) and protein (total and cell surface) level." (PMID 35563741, 2022). "As a result, CD36 was proposed as a therapeutic target for obesity-associated heart disease." (PMID 36061565, 2022). "The fatty acid translocase (FAT) CD36 has been implicated in various obesity-related complications." (PMID 35348641, 2022). "However, previous studies in other populations have shown that CD36 SNPs are strongly associated with obesity, which is a major risk factor for type 2 diabetes." (PMID 36031603, 2022). "A systematic review of studies that investigated the association between CD36 and the metabolic complications of obesity, reported that CD36 may be involved in obesity-related complications in humans." (PMID 35396566, 2022).
Obesity (continued). "Moreover, CD36 deficiency attenuates obesity-associated oxidative stress in the heart by reducing NOX activity." (PMID 34206537, 2021). "Moreover, growing evidence indicates that increased levels of cluster determinant 36 (CD36) are directly linked to obesity." (PMID 34679777, 2021). "Obese patients who carry a single nucleotide polymorphism (rs1761667) in the CD36 gene exibited lower CD36 expression associated with lower oral detection for lipids and this might contribute to development of obesity." (PMID 33927690, 2021). "CD36 gene polymorphism −31118 G > A (rs1761667) is associated with overweight and obesity." (PMID 34827565, 2021). "CD36 deficiency prevents obesity-associated cardiac steatosis and insulin resistance." (PMID 34827565, 2021). "Here, we show that inducible LEC CD36 deletion in adult mice causes leaky lymphatic vessels in the mesenteric region, accumulation of inflamed visceral adipose tissue, and spontaneous late-onset obesity." (PMID 34099721, 2021). "Interestingly, FASN expression is directly linked to obesity and type 2 diabetes and CD36 protein expression is upregulated in both obese patients and type 2 diabetics." (PMID 32850342, 2020). "We observed that CD36 expression in adipose T cells was increased in mice fed a western diet, which may have relevance to the findings that associate higher expression of CD36 in adipocytes and adipose tissue macrophages to obesity and inflammation." (PMID 31035848, 2019). "Further, variations in the CD36 taste receptor gene have been associated with obesity in humans." (PMID 30945140, 2019). "In presence of excess exogenous FA concentrations, CD36 is dysfunctional and suppresses AMPK, and might contribute to the reported association of CD36 variants with metabolic complications of obesity in humans." (PMID 29167646, 2017). "As a consequence of its many ligands and functions, CD36 could impact on a wide range of dysmetabolic conditions associated with obesity, such as dyslipidaemia, insulin resistance, diabetes, inflammation, atherosclerosis and cancer." (PMID 29270130, 2017). "Previously, we have shown that CD36 deficiency reduces lipid accumulation in peripheral organs of lean mice, but the question whether CD36 expression alters obesity-associated oxidative stress and lipotoxicity is still unknown." (PMID 27195707, 2016). "We also studied the association between rs1761667 polymorphism of CD36 gene and obesity." (PMID 26556365, 2015). "We report that rs1761667 polymorphism of CD36 gene and oro-gustatory thresholds for fat might play a significant role in the development of obesity in young teenagers." (PMID 26556365, 2015). "However, obesity has been proved to cause a permanent translocation of CD36 from intracellular storage compartments to the sarcolemma, leading to the excessive FA uptake into the heart." (PMID 26036798, 2015). "Based on the key role of CD36 in the initiation of obesity-related cardiomyopathy, we hypothesized that cardiospecific CD36 deficiency in the setting of obesity would attenuate cardiac remodeling and dysfunction by reducing lipotoxicity and oxidative stress." (PMID 26036798, 2015). "Thus, our results revealed a tight association between CD36 and cardiac remodeling in the setting of obesity." (PMID 26036798, 2015). "CD36 has been associated with obesity and diabetes in human liver diseases, however, its role in age-associated nonalcoholic fatty liver disease (NAFLD) is unknown." (PMID 24751397, 2014). "In conclusion, we report in this study, for the first time, that obesity in P. obesus is associated with increased oro-gustatory perception of dietary fat and upregulated Ca2+ signaling in circumvallate papillae, associated with altered CD36 expression." (PMID 23936306, 2013).
Obesity (continued). "Human clinical studies have also examined CD36 polymorphisms associated with enhanced atherosclerotic cardiovascular diseases, type II diabetes, oral fat perception, fat preference and obesity in African-Americans and protection from malaria." (PMID 24970143, 2012). "Additionally, obesity has been found to be closely associated with CD36." (PMID 40552158, 2025). "Furthermore, a subpopulation of CD206hiEndothelial cell adhesion molecule (ESAM)+ liver macrophages has been recently revealed to be metabolically responsive through the expression of CD36, which promotes oxidative stress associated with diet‐induced obesity and hepatic steatosis." (PMID 41163804, 2025). "Another study has been conducted on the association between single-nucleotide polymorphisms (SNPs) in the CD36 gene, including rs1761667 (A/G substitution), and cardiovascular diseases, type 2 diabetes, metabolic syndrome, consumption of total fat, fat taste perception, or obesity." (PMID 37239003, 2023). "Therefore, in this study, we determined whether specific blocking of TSP1/CD36 interaction with a CD36 peptide can ameliorate obesity-associated inflammation and IR in a diet-induced obesity mouse model." (PMID 37980376, 2023). "Therefore, we first determined whether CD36 peptide treatment could attenuate obesity-associated kidney structural or functional changes." (PMID 37980376, 2023). "However, a previous study has showed that MFG-E8 could promote fatty acid uptake and cause obesity in mice by inducing the translocation of CD36 and FATP1 into cell surface." (PMID 35769208, 2022). "This present study presented the first evidence which suggests that CD36 plays an important role in lipid metabolism and CD36 gene polymorphisms and methylation might be a factor predisposing to obesity and its related complication type 2 diabetes in a Senegalese population." (PMID 35982478, 2022). "Consequently, high insulin levels observed in obesity may contribute to lysosomal dysfunction by generating an increase in the expression CD36, which together contribute to obesity-associated dyslipidemia." (PMID 34957117, 2021). "The observed association of low CD36 and high fat liking in progranulin-deficient mice was in accordance with previous studies, which revealed that CD36 expression in taste buds decreased upon high-fat dieting and was permanently low in models of obesity, such as ghrelin knockout." (PMID 34836380, 2021). "Additionally, CD36 genetic variations have been associated with obesity in humans." (PMID 30945140, 2019). "CD36 encodes a membrane glycoprotein that belongs to the class B scavenger receptor family that may play an important role in lipid metabolism in humans and may be involved in obesity-related complications." (PMID 24579084, 2014). "Obesity and adipose tissue inflammation was compared in CD36 deficient (CD36 KO) mice and wild type (WT) mice fed a high fat diet (60% kcal fat) for 16 weeks and the inflammatory response was studied in primary adipocytes and macrophages isolated from CD36 KO and WT mice." (PMID 22615812, 2012). "Similarly, the overexpression of the well-known ubiquitous scavenger receptor CD36 in the livers of obese Pgp-deficient mice, may contribute to the onset of obesity by favouring lipid accumulation in tissues." (PMID 21949682, 2011). "Understanding the implications of these absences on CD36 function is essential for elucidating their potential role in obesity development and fat accumulation processes." (PMID 40087777, 2025). "In our study, we observed a significant increase in CD36 protein levels in pancreatic tissue, epididymal adipose tissue, and ATMs in obesity-related SAP." (PMID 40331957, 2025). "Studies have shown that genetic deletion of CD36 can prevent the onset of cardiac hypertrophy and dysfunction in murine models of obesity and diabetes." (PMID 40027179, 2025).
Obesity (continued). "CD36 is involved in inflammation, metabolism, and immunity, and it plays a role in atherosclerosis, diabetes, obesity, and certain cancers." (PMID 41465460, 2025). "The inhibition of CD36 relieved lipid accumulation and improved podocyte dysfunction in obesity-related glomerulopathy." (PMID 39810230, 2025). "The inhibition of CD36 or its receptor has been reported to protect against obesity, insulin resistance, and inflammation." (PMID 40286055, 2025). "Future studies should further investigate the potential VAT/FA/CD36/Kir2.1 axis in the context of obesity-induced endothelial dysfunction." (PMID 40996861, 2025). "Together, these findings point to a role for a CD36-mediated FA uptake mechanism initiated by VAT that results in the impairment of Kir2.1, prompting further investigation into a VAT/FA/CD36/Kir2.1 axis as a contributor to obesity-endothelial dysfunction." (PMID 40996861, 2025). "Inhibiting CD36 with SAB in mice with diet-induced obesity reduced visceral fat accumulation and improved insulin resistance." (PMID 40565598, 2025). "The present in vitro study sheds light on a novel VAT/FA/CD36/Kir2.1 axis in obesity-induced endothelial dysfunction, although we have yet to establish a concrete role for this axis in vivo." (PMID 40996861, 2025). "In vivo, mice with inducible deletion of CD36 in LECs manifested compromised integrity of the collectors, spillover of lymph in the mesentery, and spontaneous obesity." (PMID 40081576, 2025). "The role of CD36 in obesity-related MAFLD has been extensively studied, and it can even be a therapeutic target." (PMID 40562101, 2025). "Possibly, once adipose tissue reaches its expansion limit, CD36-mediated mechanisms drive the spillover of lipids into ectopic sites, exacerbating obesity complications." (PMID 41344388, 2025). "Among these, Ov-ERV-R13-CD36, which is specifically classified as a beta retrovirus, was selected for further analysis due to its location in CD36 gene, known for its role in fat metabolism, obesity (OB), body weight (BW), and body condition score (BCS)." (PMID 40087777, 2025). "Ob/ob mice exhibit elevated CD36 protein levels in their livers, and the CD36 content in the livers of patients with grade III obesity (BMI ≥35) is positively associated with liver fat content." (PMID 40552158, 2025). "As previously shown, CD36, a transmembrane glycoprotein, plays a pivotal role in lipid uptake and utilization in diabetes, obesity, and other conditions 13,27,28." (PMID 40607256, 2025). "In the liver and adipose tissue, elevated CD36 expression is an unfavorable signal, as it enhances lipid uptake, contributing to obesity and fatty liver disease." (PMID 40837406, 2025). "Based on our present findings, future studies will focus on the role of endothelial CD36-mediated endothelial dysfunction in obesity and decipher the role of VAT and SAT in vivo." (PMID 38586877, 2024). "Future studies will be aimed at deciphering the exact mechanisms of 1) VAT-mediated upregulation of CD36, and 2) CD36-mediated impairment of endothelial Kir2.1 in obesity." (PMID 38586877, 2024). "In particular, CD36 is a marker for metabolically activated macrophages (MMe), which are involved in the development of obesity." (PMID 38813101, 2024). "Furthermore, some studies have suggested that sodium valproate-induced obesity and weight gain might be linked to CD36 and PPARγ polymorphisms, with these genetic factors potentially serving as predictive markers for sodium valproate-induced obesity in Chinese Han epilepsy patients." (PMID 39121110, 2024). "In these experiments, IX administration reduced expression levels of PPAR α and CD36 mRNA in the intestine concomitant with increased Parabacteroides and decreased Lactobacillus, and the mice showed resistance to obesity by HFD." (PMID 39064713, 2024).
Obesity (continued). "We suggest here that Endo1, most likely by controlling CD36 cell surface abundance and lipid uptake in adipocytes, dissociates obesity from diabetes and that its absence participates in metabolically healthy obesity." (PMID 38716728, 2024). "A previous study using a high-fat diet to induce obesity in mice demonstrated, in line with our finding, that genistein treatment reduced Cd36 mRNA expression." (PMID 39351533, 2024). "Consistent with this, the increased expression of Endo1 in the white adipose tissue (WAT) during HFD would likely lead to an imbalance in the localization of CD36 on the surface of adipocytes in obesity, contributing to adipose tissue dysfunction." (PMID 38716728, 2024). "NEGR1 has been suggested to regulate cellular fat content via CD36 expression regulation, and its gene NEGR1 has been identified as a risk locus for obesity in genome‐wide association studies." (PMID 38420755, 2024). "In mice datasets, we identified CD36, an obesity influenced gene that codes for a receptor of fatty acids, which was also detected in human datasets and in tissue validation although not significant." (PMID 38918843, 2024). "This alludes to a potential complex role for VAT-induced upregulation of CD36 in mediating Kir2.1 impairment in obesity in vivo although our studies in isolated arteries of CD36 KO mice further support such a role is present." (PMID 38586877, 2024). "The importance of CD36 in mediating obesity-induced endothelial dysfunction in VAT arteries was additionally supported by our ex vivo studies where CD36 ablation restored VAT artery endothelial function in a Kir2.1/eNOS-dependent manner." (PMID 38586877, 2024). "Previous studies have indicated that fatty acid oxidation and the activity of enzymes involved in mitochondrial fatty acid transport and oxidation, such as CPT-1α, PPARα, and CD36, are lower in skeletal muscle during obesity and insulin resistance." (PMID 39596482, 2024). "Future studies should be aimed at determining the specific mechanisms by which VAT regulates CD36 in endothelium and potentially other AT cells as well as how CD36 promotes Kir2.1 impairment in obesity-induced endothelial dysfunction." (PMID 38586877, 2024). "As most research on FABP4 and CD36 pertains to obesity, we compared the body mass index (BMI) of 30 SARIFA-positive and 30 SARIFA-negative patients." (PMID 38216952, 2024). "Reduction of CD36 expression on the tongue has been shown to attenuate linoleic acid preference in obesity-prone and obesity-resistant rats." (PMID 39519538, 2024). "Together, our findings reveal a new role for CD36 in obesity-induced endothelial dysfunction that is likely driven by VAT and results in Kir2.1 and endothelial dysfunction." (PMID 38586877, 2024). "Fatty acid translocase (CD36) gene expression was related to insulin resistance, obesity, and liver steatosis." (PMID 37426418, 2023). "The expression of the fatty acid transporter Cd36 was significantly downregulated in the livers of KO mice compared to WT controls, possibly because of their leaner phenotype, as the expression of CD36 is promoted during obesity." (PMID 37121509, 2023). "Further studies are necessary to determine the molecular regulation of CD36 expression under different FA loading conditions and its contribution to tissue-specific functions to understand how CD36 affects specific obesity-related phenotypes and complications." (PMID 36979708, 2023). "The possible role of fatty acid translocase (CD36) in the treatment of obesity has gained increasing research interest since researchers recognized its coordinated function in fatty acid uptake and oxidation." (PMID 36979708, 2023). "It is possible that due to the reduced Cd36 expression levels in intestines, Ifrd1 Ifrd2 dKO mice accumulated lower amounts of body fat and were resistant to diet-induced obesity also because of limited intestinal fat uptake." (PMID 37603466, 2023).